SNHG17 (small nucleolar RNA host gene 17)
Gene: Long non-coding RNA gene on chromosome 20 (38,419,638 to 38,435,409, reverse strand). Ensembl gene ENSG00000196756.
Gene Ontology:
Biological process: RNA processing
Cellular component: nucleolus
Diseases named in the same sentence as SNHG17 in open-access papers:
SNHG17 is named in the same sentence as 37 diseases in open-access papers, as found by Europe PMC text mining. Sharing a sentence is not in itself a finding about the gene and the disease. The quoted sentences say what the papers report.
gastric cancer (16 papers, 2020 to 2023). A primary or metastatic malignant neoplasm involving the stomach. "Recent studies suggest that abnormal expression of SNHG17 is associated with several tumors, including gastric cancer, non-small-cell lung cancer, colorectal cancer, melanoma, breast cancer, glioma, and tongue squamous cell carcinoma." (PMID 34429400, 2021). "In addition, SNHG17 can be an independent prognostic factor in hepatocellular carcinoma, renal cell carcinoma, colorectal cancer, gastric cancer, and melanoma and a diagnostic predictor in cervical and gastric cancers." (PMID 36185210, 2022). "SNHG17 has emerged as an oncogene in several cancer types, including colorectal cancer, hepatocellular carcinoma, gastric cancer, and breast cancer, as it exhibits increased expression levels in these tumor types." (PMID 38098044, 2023). "For instance, in gastric cancer, SNHG17 has been identified as an enhancer of resistance to the widely-used chemotherapy drug cisplatin." (PMID 38098044, 2023). "For example, SNHG17 has been found to be significantly higher in breast cancer, colorectal cancer, gastric cancer, and prostate cancer." (PMID 35118117, 2021). "Previous studies have discovered SNHG17 plays an important role in the development of cancer, such as colorectal cancer, non-small-cell lung cancer, gastric cancer, breast cancer, melanoma, and glioma." (PMID 34557456, 2021). "For example, the high expression of SNHG17 was associated with the increased invasion depth, lymph node metastasis, and advanced TNM stage of gastric cancer." (PMID 35118117, 2021). "Small nucleolar RNA host gene 17 (SNHG17) belongs to lncRNAs, and it has been reported in breast cancer and gastric cancer." (PMID 33292246, 2020). "SNHG17 was reported to promote gastric cancer progression by epigenetically silencing of p15 and p57, and it was an unfavorable prognostic factor in colorectal cancer and gastric cancer." (PMID 33102573, 2020). "Previously, several works demonstrated the high expression and oncogenic properties of SNHG17 in cancers such as gastric cancer and colorectal cancer." (PMID 32447342, 2020). "SNHG17, a member of the Small Nucleolar RNA Host Gene family, is aberrantly expressed in cancer cells from multiple tumor types, including colorectal, lung, and gastric cancer." (PMID 38098044, 2023). "SNHG17 has been shown to promote gastric cancer progression by downregulation of p15 and p57." (PMID 34429400, 2021). "SNHG17 has been reported to elicit oncogenic influences in gastric cancer and colorectal cancer." (PMID 32447342, 2020). "Moreover, SNHG17 was identified as an unfavorable prognostic predictor in gastric cancer and colorectal cancer." (PMID 32351538, 2020). "SNHG17 promotes cell proliferation in colorectal cancer, regulates cell invasion and migration in breast cancer, and affects cell cycle in gastric cancer." (PMID 33519911, 2020). "For example, SNHG17 accelerates the progression of gastric cancer by downregulating p15 and p57." (PMID 33292246, 2020). "Previous studies validated that SNHG17 served as an oncogene in gastric cancer and melanoma." (PMID 32883232, 2020). "For example, SNHG17 is abnormally expressed in gastric cancer cells and predicts prognosis." (PMID 33292246, 2020). "Notably, the elimination of SNHG17 in gastric cancer cells inhibited chromosomal aberrations after H. pylori infection and overexpression of SNHG17 was correlated with a poor prognosis in patients with gastric cancer." (PMID 36769214, 2023). "Small nucleolar RNA Host Gene 17 (SNHG17), an important lncRNA, was proven to play oncogenic role in non-small cell lung cancer, gastric cancer, colorectal cancer and melanoma." (PMID 32042267, 2020). "Moreover, we showed that knocking down SNHG17 reduced SNORA71B in NSCLC, gastric cancer, and colorectal cancer cell lines (A549, MGC-803, and DLD1), in which SNHG17 was reported to exert oncogenic functions by former studies." (PMID 32447342, 2020).
gastric cancer (continued). "In addition, upregulation of lncRNA small nucleolar RNA host gene 17 (SNHG17) is observed in various cancers including NSCLC, gastric cancer (GC), and GBM." (PMID 38204968, 2023).
colorectal cancer (14 papers, 2020 to 2023). A primary or metastatic malignant neoplasm that affects the colon or rectum. "For example, in colorectal cancer, SNHG17 competes with the E3 ligase Trim23 to bind Pescadillo (PES1), protecting PES1 from degradation." (PMID 36185210, 2022). "On human chromosome 20, small nucleolar RNA host gene 17 (SNHG17) is highly expressed in colorectal cancer tissues." (PMID 36618403, 2022). "SNHG17 has been reported as a candidate oncogene in several cancer types, however, its regulatory role in colorectal cancer (CRC) is unclear." (PMID 34782005, 2021). "The lncRNA small nucleolar RNA host gene 17 (SNHG17), located on chromosome 20q11.23, was detected in patients with colorectal cancer." (PMID 33519911, 2020). "SNHG17 binds to EZH2 and suppresses p57 to stimulate the development of colorectal cancer." (PMID 33519911, 2020).
melanoma (9 papers, 2020 to 2024). A malignant, usually aggressive tumor composed of atypical, neoplastic melanocytes. "Subsequent research found that SNHG17 was upregulated in numerous tumor types, including gastric and lung cancer, osteosarcoma, melanoma, and hepatocellular carcinoma." (PMID 37755396, 2023). "In melanoma, SNHG17 is upregulated by the transcription factor STAT3, contributing to melanoma progression by enhancing PI3K-AKT signaling and its growth-promoting effects that also facilitate cellular invasiveness and migration." (PMID 37755396, 2023). "SNHG17 upregulation is positively correlated with lymph node metastasis and decreased OS in melanoma patients, and SNHG17 expression is an independent predictor of melanoma prognosis." (PMID 35248073, 2022). "Mechanistic studies indicated that STAT3-induced upregulation of SNHG17 contributed to melanoma progression by promoting PI3K-AKT signaling." (PMID 35248073, 2022). "Further, SNHG17 influences melanoma cell proliferation and migration through PI3K-AKT signaling." (PMID 34429400, 2021). "Similarly, SNHG17, a member of the SNHG family, is highly expressed in multiple cancers, including melanoma and lung adenocarcinoma." (PMID 38831187, 2024).
glioma (7 papers, 2020 to 2025). A benign or malignant brain and spinal cord tumor that arises from glial cells (astrocytes, oligodendrocytes, ependymal cells). "Additional studies revealed that SNHG17 is highly expressed in both glioma tissues and cell lines, and its expression is associated with malignant features of gliomas." (PMID 35248073, 2022). "Functional experiments showed that SNHG17 knockdown significantly inhibited the proliferation, migration, and invasion of glioma cells, while promoting apoptosis." (PMID 35248073, 2022). "SNHG17 subsequently regulates cell proliferation of glioma cells via the miR-506-3p/CTNNB1/Wnt/β-catenin signaling pathway." (PMID 35248073, 2022). "Analysis of the GEPIA database revealed a significant upregulation of SNHG17 in glioma compared to control samples." (PMID 35248073, 2022). "We carried out functional assays to verify the effects of up-regulation of SNHG17 on glioma progression." (PMID 32009853, 2020). "All the data suggested that SNHG17 activated Wnt/β-catenin signaling pathway to promote the progression of glioma." (PMID 32009853, 2020). "All the data implied that YY1 increased the expression of SNHG17 through binding with SNHG17 promoter to boost the development of glioma." (PMID 32009853, 2020). "Subsequently, we performed rescue assays to illustrate how YY1 regulated the process of glioma by modulating SNHG17 expression." (PMID 32009853, 2020). "To validate this assumption, we conducted the RT-qPCR assays and found that only miR-506-3p, miR-330-3p, miR-3619-5p and miR-2116-3p were up-regulated by SNHG17 knockdown in glioma cells." (PMID 32009853, 2020). "All in all, SNHG17 was highly expressed in glioma and down-regulation of SNHG17 blocked glioma progression." (PMID 32009853, 2020). "Rescue experiments illustrated that overexpression of CTNNB1 offset the inhibitory effect resulted from SNHG17 depletion in glioma cells." (PMID 32009853, 2020). "To further investigate why SNHG17 activated Wnt/β-catenin signaling pathway in glioma, we hypothesized that SNHG17 might influence CTNNB1 expression to activate Wnt/β-catenin signaling pathway." (PMID 32009853, 2020). "Mechanistically, SNHG17 activated Wnt/β-catenin signaling pathway in glioma." (PMID 32009853, 2020). "SNHG17 regulates cell functions by acting as a molecular sponge for miRNAs in breast cancer, tongue squamous cell carcinoma, and glioma." (PMID 33519911, 2020). "Inhibition of SNHG17 blocked cell proliferation and accelerated cell apoptosis in glioma cells." (PMID 32009853, 2020). "Furthermore, we verified that SNHG17 negatively regulated miR-506-3p expression meanwhile miR-506-3p negatively regulated CTNNB1 expression in glioma." (PMID 32009853, 2020). "All the data suggested that SNHG17 activated Wnt/β-catenin signaling pathway in glioma." (PMID 32009853, 2020). "In present study, SNHG17 expression was identified to be elevated in glioma tissues and cell lines." (PMID 32009853, 2020). "In conclusion, SNHG17 activated Wnt/β-catenin signaling pathway to aggravate the course of glioma." (PMID 32009853, 2020). "Given that CTNNB1 was the mRNA of β-catenin; we speculated SNHG17 might regulate Wnt/β-catenin signaling pathway via up-regulating the expression of CTNNB1 in glioma." (PMID 32009853, 2020). "For instance, LINC00210 activated Wnt//β-catenin activity and contributed to process of liver tumor by targeting CTNNB1P1.In this study, we found that LiCl could rescue the impacts of SNHG17 on the course of glioma and then we delved into how SNHG17 had impacts on Wnt signaling pathway." (PMID 32009853, 2020). "Besides, overexpression of SNHG17 contributed to proliferation in glioma." (PMID 32009853, 2020). "Thus we further explored the detailed function of SNHG17 in glioma." (PMID 32009853, 2020). "For instance, SNHG17, as a sponge of miR-506-3p, was clarified to upregulate the expression of CTNNB1 in glioma." (PMID 34497156, 2021).
hepatocellular carcinoma (7 papers, 2020 to 2023). A malignant tumor that arises from hepatocytes. "SNHG17 has subsequently also been found to be overexpressed in lung cancer, GC, hepatocellular carcinoma, osteosarcoma and other tumors, and its expression levels have been reported to be associated with a poor prognosis." (PMID 35248073, 2022). "Analysis of human hepatocellular carcinoma (HCC) tissues revealed that SNHG17, LRPPRC, and c-Myc were significantly upregulated in HCC, and they showed a positive correlation with each other." (PMID 34671012, 2021). "BDE-47 induced the expression of SNHG17 and LINC01348, respectively, an oncogene and a tumor suppressor in hepatocellular carcinoma (HCC)." (PMID 36430946, 2022). "However, the expression pattern and biological function of SNHG17 in hepatocellular carcinoma (HCC) remain unclear." (PMID 34557456, 2021).
prostate carcinoma (6 papers, 2021 to 2024). A carcinoma that arises from epithelial cells of the prostate gland. "Interestingly, the upregulation of SNHG17 is associated with increased drug resistance in astrocytoma and prostate cancer." (PMID 36185210, 2022). "Reports suggested that SNHG17 is significantly upregulated in both prostate cancer tissues and cells, especially in aggressive and metastatic cells." (PMID 35248073, 2022). "Previous literature describes that SNHG17 in prostate cancer increases the expression of its homolog snoRA71B through a positive feedback loop, which promotes tumor progression." (PMID 36185210, 2022). "For example, a present study revealed that SNHG17 could aggravate prostate cancer progression through regulating its homologue SNORA71B via a positive feedback loop." (PMID 38680032, 2024). "The prognostic value, biological function, and regulatory network of SNHG17 in prostate cancer still need to be further validated by experiments, although we have done some work to verify our hypothesis." (PMID 35864871, 2022). "In the present study, we have concluded some similar results as literatures previously reported, that expression of SNHG17 was found to be significantly correlated with the progression of prostate cancer, and demonstrated great prognostic values for patients with PC." (PMID 35864871, 2022). "Mechanistic studies indicated that SNHG17 may regulate prostate cancer development via the Wnt/β-catenin pathway." (PMID 35248073, 2022). "Additionally, we observed that the expression of SNHG17, UBE2M, and OTUB1 was significantly correlated with a decreased infiltrating level of immune cells, indicating the immunological role of SNHG17 and its ceRNA regulatory network in prostate cancer." (PMID 35864871, 2022). "In addition, SNHG17 aggravates prostate cancer progression by positively regulating its homolog SNORA71B." (PMID 34782005, 2021). "Through this ceRNA network, SNHG17 may promote the progression of prostate cancer and modulate the microenvironment of PC tumors, and targeting SNHG17 may suppress the malignancy of prostate cancer, activate antitumor immunity, and enhance the therapeutic effects of immune checkpoint blockade." (PMID 35864871, 2022). "Additionally, we explored novel mechanisms that may further uncover the carcinogenetic functions of SNHG17 in prostate cancer." (PMID 35864871, 2022). "Taken together, SNHG17 is very likely to influence immune infiltration by upregulating the expression of OTUB1 and UBE2M in prostate cancer." (PMID 35864871, 2022). "Mechanistically, SNHG17 and its homolog SNORA71B were transactivated by signal transducer and activator of transcription 5A (STAT5A), and SNHG17 sponged with miR-339-5p and released the expression of STAT5A, thereby forming a regulatory loop and exacerbating prostate cancer progression." (PMID 35864871, 2022).
breast carcinoma (5 papers, 2020 to 2021). "Recently, SNHG17 was reported as an oncogene in prostate cancer, breast cancer, glioma." (PMID 33292246, 2020). "Moreover, SNHG17 is discovered to participate in the development of breast cancer to become a useful and valuable biomarker." (PMID 33292246, 2020).
lung adenocarcinoma (4 papers, 2021 to 2025). A carcinoma that arises from the lung and is characterized by the presence of malignant glandular epithelial cells. "In lung adenocarcinoma, SNHG17, which reduces miR-193a-5p levels, is overexpressed in lung adenocarcinoma tissues and is associated with tumor-node-metastasis stage and poor prognosis." (PMID 40161373, 2025). "SNHG17 is frequently upregulated in LUAD (lung adenocarcinoma) and LUSC (lung squamous cell carcinoma) tissues compared with their paired non cancer tissues." (PMID 36635762, 2023). "In lung adenocarcinoma cell lines, WLS is upregulated by small nucleolar RNA host gene 17 (SNHG17), the up-regulation of WLS could reverse the inhibition of proliferation and promote apoptosis effects of SNHG17 down-regulation." (PMID 34760348, 2021).
non-small cell lung carcinoma (4 papers, 2020 to 2021). A group of at least three distinct histological types of lung cancer, including non-small cell squamous cell carcinoma, adenocarcinoma, and large cell carcinoma. "For example, overexpressed SNHG17 was shown to regulate cell proliferation and migration of non-small cell lung cancer (NSCLC)." (PMID 34429400, 2021). "Genomic amplification was reported as one cause of SNHG17 overexpression in non-small-cell lung cancer (NSCLC), and knockdown of SNHG17 inhibited the proliferation and migration and promoted the apoptosis of NSCLC cells with unknown mechanisms." (PMID 34671012, 2021).
ovarian carcinoma (4 papers, 2022 to 2025). A malignant neoplasm originating from the surface ovarian epithelium. "Studies have indicated that SNHG17 is upregulated in ovarian cancer and acts as a molecular sponge for miR-214-3p, relieving miR-214-3p’s inhibitory effect on the cell cycle regulator CDK6, thereby promoting the growth of ovarian cancer cells." (PMID 38439898, 2024). "SNHG17 downregulation inhibited the tumorigenesis of epithelial ovarian cancer via the regulation of miR‐485‐5p/AKT1 axis." (PMID 38680032, 2024). "When exposure to oestrogen, exosomal SNHG17 promoted ovarian cancer cell proliferation, migration, invasion and epithelial‐mesenchymal transition (EMT) in vitro, and tumour growth and lung metastasis in vivo by accelerating M2‐like phenotype of macrophages." (PMID 38680032, 2024). "A study investigating data from the TCGA database identified SNHG17 as an autophagy-related gene in ovarian cancer." (PMID 35248073, 2022). "In Pan’s study, SNHG17 has further been found to suppress apoptosis and promote ovarian cancer cell proliferation in vitro and vivo." (PMID 35248073, 2022). "Mechanically, transcription factor STAT3 directly binds to the promoter region of SNHG17 and promotes its transcription, and SNHG17 subsequently regulates cell cycle progression and proliferation of ovarian cancer cells via the miR-214-3p/CDK6 axis." (PMID 35248073, 2022). "Consistently, our results confirm the oncogenic role of SNHG17 in ovarian cancer, that is exosomal SNHG17 could promote ovarian cancer cell proliferation, migration, invasion and EMT in vitro and tumour growth and metastasis in vivo." (PMID 38680032, 2024). "In the present study, we discovered that SNHG17 was upregulated in ovarian cancer." (PMID 38680032, 2024). "SNHG17 is highly expressed in ovarian cancer tissues and cells." (PMID 35248073, 2022). "There results demonstrate a novel mechanism that exosomal SNHG17 exerts an oncogenic effect on ovarian cancer via the CCL13–CCR2–M2 macrophage axis upon oestrogen treatment, of which SNHG17 may be a potential biomarker and therapeutic target for ovarian cancer responded to oestrogen." (PMID 38680032, 2024). "In addition, the role of SNHG17 has also been investigated in ovarian cancer." (PMID 38680032, 2024).
colorectal adenocarcinoma (3 papers, 2020 to 2023). The most common type of colorectal carcinoma. "Colorectal adenocarcinoma cell proliferation and migration are facilitated by SNHG17 through inhibition of miR-23a-3p, which modifies CXCL12-mediated angiogenesis." (PMID 38004422, 2023). "Small nucleolar RNA host gene 17 (SNHG17), belonging to lncRNAs, is highly expressed in colorectal adenocarcinoma (CRA) cells." (PMID 35935996, 2022).